TNF (tumor necrosis factor)
Diseases named in the same sentence as TNF in open-access papers (continued):
Sharing a sentence is not in itself a finding about the gene and the disease.
Stroke (continued). "Anti-inflammatory approaches that target neutrophils, macrophages, and T cells, inhibition of cytokines such as IL-6, IL-17, and TNF-α, or modulate T-reg cells, have shown protective effects in experimental stroke, preventing GI barrier damage and permeability associated with BT." (PMID 39767686, 2024). "Therefore, a TNF alpha inhibitor such as etanercept can stop the positive feedback loop causing the excess TNF alpha production in post-stroke pain by being administered directly through the CSF." (PMID 37065345, 2023). "In addition to serum TNF-α, the changes in other biomarkers were also associated with the significant improvement in post-stroke function." (PMID 37731856, 2023). "Results also indicated that TNF-alpha rs1800629 G > A genotype distribution was associated with age of stroke patients, and that the TNF- alpha rs1800629 G > A genotype distribution was significant different in cases with elevated HbA1c and cases with normal HbA1c." (PMID 37240845, 2023). "In addition to serum TNF-α, the concentration changes of other biomarkers were significantly associated with functional improvement after stroke." (PMID 37731856, 2023). "Studies have shown that chronic inflammatory conditions, such as post-stroke syndrome, are due to TNF alpha chronically activating microglia with a damage-associated molecular patterns (DAMP) molecule, thereby producing excess amounts of TNF alpha in the cerebrospinal fluid (CSF)." (PMID 37065345, 2023). "Previous studies also showed that a possible mechanism underlying EC death post-stroke could be attributed to M1 microglia-derived TNF-α induced endothelial necroptosis and increased breakdown of BBB." (PMID 36186129, 2022). "Our study showed that TNF-α levels were increased in the SAP group, which suggested that the increase of TNF-α present during the late stage of stroke could also be linked to SAP, as the duration of SIIS still remained unknown." (PMID 36439158, 2022). "Lower TNF-α promotor methylation further correlates to increased stroke risk in patients." (PMID 36361891, 2022). "Similarly, treatment for those with autoinflammation and vasculitis who escape efficacy from anti-TNF (e.g. by development of anti-drug antibodies) have a guarded prognosis, with significant risk of stroke or death." (PMID 35529868, 2022). "In addition, function recovery of stroke by wasp venom treatment was associated with a decrease in TNF-α, IL-1β, IL-6 and inhibition activated microglia as well as apoptosis." (PMID 35171059, 2022). "Various studies have shown an association between TNFα and stroke injury." (PMID 33643574, 2021). "Although some evidence suggests that TNFα gene polymorphism could be a predictor of the recurrent TIAs, the value of this factor for prediction of stroke risk is unequivocally assessed and requires further studies." (PMID 31701356, 2020). "In a logistic regression analysis adjusted for age, stroke severity, pneumonia, leukocyte count, plasma interleukin-6, and TNFα release ex vivo, a higher GC sensitivity index was associated with a higher risk of poor outcome after stroke (OR 2.32, 95% CI 1.21–4.45, P = 0.01)." (PMID 32107751, 2020). "Furthermore, DMARD and TNF-α antagonists are associated with reduced risk of myocardial infarction, stroke, and cardiovascular death." (PMID 33390933, 2020). "Higher serum TNF-α level was also associated with poor outcomes after stroke." (PMID 31183363, 2019). "Indeed, we showed that the compromised intestinal barriers following stroke in older animals were associated with the early and increased production of pro‐inflammatory TNF‐α." (PMID 31199577, 2019). "Moreover, polymorphisms of the promoter IL‐6 gene have been proved to be associated with the presence of stroke while polymorphisms of the TNF gene and IL‐1 gene have been suspected to be associated with ischemic stroke." (PMID 29484258, 2018).
Stroke (continued). "Furthermore, we detected a 10-fold increase in penumbral TNF-α in MCAO stroke brains associated with a dramatic NFκBp65 activation." (PMID 29654318, 2018). "Importantly, both TNF-α and IL-6 are strongly implicated in the vascular permeability in rodents subjected to stroke." (PMID 29452577, 2018). "Among the cytokines known to be associated with inflammation in stroke, interleukin-1 (IL-1) and TNF-α were reported to aggravate cerebral injury; in contrast, interleukin-6 (IL-6), interleukin-10 (IL-10), and transforming growth factor-β (TGF-β) were shown to be neuroprotective." (PMID 29090015, 2017). "However, IFN-γ and TNF-α mRNA expression was increased in patients with high stroke risk compared with those with low risk." (PMID 27115869, 2016). "The whole range of cytokine families (interleukins (IL), interferons (IFN), tumor necrosis factors (TNF), colony stimulating factors, growth factors and chemokines) have been implicated as contributors to pre-existing risk factors for stroke as well as following reperfusion." (PMID 25705177, 2015). "Paradoxically, TNF-α has a dualistic effect in stroke, since it's up-regulation has been shown to underlie LPS-induced tolerance in mice subjected to focal cerebral ischemia, whereas suppression of TNF-α signaling during ischemia confers neuroprotection after LPS preconditioning." (PMID 25972779, 2015). "Stroke and traumatic brain injury appear to be associated with abnormal TNF alpha activity." (PMID 26664821, 2015). "Increased TNF-α expression is associated with a risk of recurrent stroke." (PMID 26576074, 2015). "Furthermore, white blood cell counts and levels of C-reactive protein, serum/plasma interleukin-6 (IL-6) and tumour necrosis factor-α (TNF-α) are increased in stroke patients; several of these factors have been associated with stroke outcome and recurrence." (PMID 24889329, 2014). "TNFα, IL-17, and IL-21 have also have also been linked to stroke progression." (PMID 25309326, 2014). "The most extensively studied cytokines associated with stroke are IL-1β, IL-10, IL-6 and TNF-α." (PMID 23514014, 2013). "In addition, we and others have described several immunological markers including CD4+ T-cell counts, serum IL-6 levels, and TNF-α release by macrophages that are associated with the occurrence of infection in stroke patients." (PMID 20090932, 2010). "Upregulation of A2A receptors on neutrophils is seen following stimulation with TNF-α, which may reduce the damage caused by inflammatory immune infiltrate into the brain following stroke." (PMID 20190963, 2009). "Inflammatory factors (such as interleukins and tumor necrosis factor) produced by chronic inflammation can alter the state of vascular endothelium, activate platelets, inhibit the decomposition of fibrinogen, promote a hypercoagulable state, form blood clots, and increase the risk of stroke." (PMID 40761346, 2025). "In addition, SHBG could markedly suppress lipopolysaccharide-induced inflammatory biomarkers in macrophages and adipocytes, such as monocyte chemoattractant protein-1, TNFα, and IL-6, which have been reported to be closely related to stroke risk and prognosis." (PMID 40728963, 2025). "Notably, reduced expression of transcription factors (GATA-3, FoxP3), cytokine IL-10, and elevated mRNA expression of IFN-γ, TNF-α, and inducible nitric oxide synthase (iNOS) have been observed to increase the risk of death from stroke in these patients patients." (PMID 39217407, 2024). "In addition, A. muciniphila may inhibit the production of TNF-α and free radicals by interacting with TLRs in intestinal epithelial cells, which is associated with the reduction of serum TNF-α, IL-6, and IL-10 levels, positively impacting post-stroke recovery." (PMID 37492530, 2023).
Stroke (continued). "Understanding the physiological roles of TNF in biology gives us the opportunity to visualize how the incredibly wide range of subtle function loss reported during persistent Lyme disease, long COVID‐19,47 and post‐stroke neurological changes, might arise." (PMID 35174650, 2022). "There are reports that TNF-α and IL-6 may increase the risk of stroke." (PMID 33187206, 2020). "Moreover, increased levels of TNF-α in the serum and CSF of subjects affected by stroke are associated with a worsening of neurological symptoms, increased infarct area, and poorer outcome at 3 months in research including severe strokes and patients with impaired white matter." (PMID 32899616, 2020). "Whencohort studies were analyzed, TNF inhibitors were associated with reduced risk ofall cardiovascular events (pooled and adjusted RR 0.46, 95% CI 0.28 to 0.77),myocardial infarction (pooled and adjusted RR 0.81 95% CI 0.68 to 0.96) and stroke(pooled and adjusted RR 0.69, 95% CI 0.53 to 0.89)." (PMID 28099601, 2016). "Besides, if these TNF-α promoter functional polymorphisms could potentially contribute to the etiology of stroke in the Asian population is still needed to be illuminated." (PMID 23050663, 2012). "However, higher circulating levels of TNF-α might be expected to be associated with increased stroke risks based on experimental evidence, but some epidemiologic evidence is of no significance." (PMID 23050663, 2012). "TNF-α and IL-6 both exhibited a rapid exponential rise in concentration within the first 6 hours following simulated stroke onset, with their peaks occurring within the early inflammatory window (6–24 hours)." (PMID 41557608, 2026). "Ferroptotic cell death releases DAMPs (damage‐associated molecular patterns), which stimulate microglial activation and inflammatory cytokine release (e.g., IL‐1β, TNF‐α), aggravating neuroinflammation and secondary neuronal injury post‐stroke." (PMID 41540791, 2026). "This delay, driven by cumulative exposure to TNF-α/IL-6 and implemented via a Hill function with a transcriptional lag, mirrors reported kinetics in stroke patients and experimental models, where IL-10 peaks between 36–60 hours post-insult." (PMID 41557608, 2026). "The levels of IL-1β and TNF-α are found to increase in the cerebrospinal fluid, peaking in the days following the stroke." (PMID 40364646, 2026). "The combined effects of IL-6 and TNF-α levels provide important insight into how UMC119-06 influences immune modulation in stroke recovery." (PMID 41583506, 2026). "Within 6 hours of stroke onset, there is an increase in serum levels of TNF-α, which remain elevated for 10 days." (PMID 40364646, 2026). "These dynamics were captured under initial cytokine conditions of 0.1 nM (TNF-α), 0.05 nM (IL-6), and 0.01 nM (IL-10), using parameter values derived from stroke literature and cross-validated through simulation stability." (PMID 41557608, 2026). "Systemic inflammation is a primary response following stroke and can be evaluated by measuring markedly upregulated pro-inflammatory cytokines, such as TNF-α, IL-6, and IL-1β." (PMID 41598337, 2026). "On the contrary, IL-1β and TNF-α, which are upregulated in stroke tissue between 24 and 48 h after reperfusion and coincide with immune cell infiltration into the CNS, induce internalization and degradation of select BBB AJ and TJ proteins." (PMID 41024170, 2025). "MTC has previously been reported to suppress neuroinflammation and improve neurological function in an animal model of stroke, upregulating IL‐10 and downregulating TNF‐α expression." (PMID 39960781, 2025). "Previous research links TNFα levels to worse stroke patient outcomes, and preclinical studies demonstrate that TNFα signaling recruits immune cells to the CNS, disrupts BBB function, and promotes brain cell apoptosis during ischemic stroke." (PMID 40362325, 2025).
Stroke (continued). "In a stroke model, it improved neurological outcomes by reducing microglial activation and the expression of IL-6, IL-1β, and TNF-α, likely through inhibition of NF-κB." (PMID 40430456, 2025). "In humans, high circulating levels of TNF‐α and IL‐6 within the first 12 h after stroke are positively correlated with stroke severity and an unfavorable prognosis of stroke patients." (PMID 40804606, 2025). "For example, dim light exposure following experimental stroke or global ischemia increased proinflammatory cytokines including TNFα, IL-6, and IL-1β31,32." (PMID 41256678, 2025). "Following stroke, pro-inflammatory cytokines including TNF-α and IL-1β activate the Fas/FasL system, recruiting Fas-associated death domain (FADD) protein and procaspase-8." (PMID 41451361, 2025). "TNF-α and IL-1β, as the initiating substances in the inflammatory response chain, are involved in the whole process of stroke and can trigger an inflammatory cascade." (PMID 41471340, 2025). "Here, we examined the mRNA expressions of IL-1β, IL-6 and TNF-α after 7 d of stroke, which are crucial for the cerebral ischemia-induced neuroinflammatory process." (PMID 40004043, 2025). "During acute phases of stroke, IL-17A is involved in microglial activation and neuroinflammation, promoting the expression of TNF-α, IL-1β, and other inflammatory factors and downstream signaling molecule NF-κB p65." (PMID 40289984, 2025). "For patients who are found to be genetically or biochemically affected by cryptogenic stroke, starting TNF blockade to prevent the development of strokes is essential." (PMID 41471340, 2025). "Inflammatory factors such as HMGB-1, NMDA, MMPs, ROS, and TNF-α are known to increase during the acute phase of stroke, leading to neuronal death and blood-brain barrier disruption." (PMID 40109397, 2025). "Elevated IL-6 and TNF-alpha levels during the acute phase of stroke have been shown to exacerbate neuronal injury through various mechanisms, including apoptosis and disruption of the blood–brain barrier." (PMID 39859987, 2025). "Emerging research implicates neuroinflammatory pathways in the pathogenesis of PSD, where post-stroke immune activation mediates elevated cerebral cytokine production (IL-1β, IL-6, TNF-α)." (PMID 41164411, 2025). "In our study, the content of salivary TNF-α was significantly higher in stroke patients and correlated with cognitive impairment on the ACE-R scale." (PMID 40520895, 2025). "Previous reports from animal stroke models showed that TNF-α potentiates glutamate-induced neuronal damage following cerebral ischemia." (PMID 41148843, 2025). "In IS rat models, levels of proinflammatory cytokines TNF-α and IL-1β rise 1 h after a stroke starts." (PMID 40362186, 2025). "Previous immune‐related therapeutic approaches for stroke focus on inhibiting pro‐inflammatory cytokines, such as IL‐6 or TNF‐α, which are involved in the inflammatory response and neuroinflammation post‐stroke." (PMID 40657554, 2025). "The qPCR analysis showed that the mRNA levels of IL-6, IL-1β and TNF-α were increased in the stroke area." (PMID 40313968, 2025). "Gene expression profiling showed upregulation of proinflammatory mediators (TNF-α, IL-1β, IL-6) and the anti-inflammatory cytokine IL-10, most prominently during the first three days post-stroke, with expression levels generally higher in older patients." (PMID 41373607, 2025). "Neutrophils synthesize and secrete pro-inflammatory factors such as TNF-α, IL-1β, and IL-6 and promote the expression of MMP9, which aggravates cerebrovascular endothelial cell injury after stroke and increases the risk of hemorrhagic complications." (PMID 38740617, 2025). "We also observed the upregulation of a pro-inflammatory tumor necrosis factor alpha (TNFα) gene signature in the brains of PPARα KO mice following stroke." (PMID 40362325, 2025). "In experimental stroke models, TNF-α and IL-1 were overexpressed as early as 2 h after ICH and 24 h after IS." (PMID 40289984, 2025).
Stroke (continued). "The use of anti-inflammatory agents to modulate IL-6 and TNF-alpha levels in stroke patients is currently under investigation." (PMID 39859987, 2025). "Ischemia reperfusion significantly increases IL-6 and TNF-α levels in the injured cerebral area during the subacute phase of stroke." (PMID 40004043, 2025). "Key inflammatory cytokines in stroke include interleukin-1 (IL-1), TNF-α, interleukin-6 (IL-6), interleukin-10 (IL-10), and transforming growth factor-β (TGF-β)." (PMID 40362194, 2025). "Although the precise effects of YHJGs on AP-1 and NF-κB remain to be experimentally validated, the observed reduction in IL-1β, IL-6, and TNF-α suggests that YHJGs hold promise as a therapeutic agent for stroke-related inflammation." (PMID 41011203, 2025). "Similar to GSEA, IPA revealed significant transcriptional reprogramming of TNFα signaling gene signatures in PPARα KO stroke brains 48 h post-MCAO." (PMID 40362325, 2025). "In the GluN3A KO brain three days after stroke, inflammatory factors IL-1β, IL-6, IL-10, and/or TNFα were significantly elevated, while MEM largely prevented these increases." (PMID 41369361, 2025). "The overall expression pattern of the downstream targets indicates that TNFα is an activated upstream regulator in PPARα KO stroke brains compared with WT stroke brains (Figure A3)." (PMID 40362325, 2025). "Recent studies also suggest that elevated levels of IL-6 and TNF-α assessed on days 1 and 7 significantly correlate with greater stroke severity and worse functional outcomes, as indicated by higher NIHSS and mRS scores." (PMID 40305179, 2025). "We determined the elevated gene expression of pro-inflammatory cytokines such as IL1α and IL1β and TNFα as soon as 6 h after stroke induction." (PMID 40332314, 2025). "During the post-stroke inflammatory cascade, cytokines such as interleukin-6 (IL-6) and tumor necrosis factor-α (TNF-α) are released, promoting oxidative stress and increasing erythrocyte membrane permeability." (PMID 40739542, 2025). "The inflammatory mediators produced in periodontal diseases, including IL-6, TNF-α, and C-reactive protein, promote atherogenesis and thromboembolic events, which can contribute to stroke pathogenesis." (PMID 40259824, 2025). "In agreement, we also observed an increased expression profile for many genes known to be upregulated by TNFα in stroke brains from PPARα KO mice." (PMID 40362325, 2025). "Microglia-specific deletion or pharmacological inhibition of HDAC3 reduces expression of TNF α, IL 1β, IL 6, and iNOS, represses NF-κB targets, shifts the microglial phenotype toward an anti-inflammatory state, and improves stroke outcomes." (PMID 40867911, 2025). "The patients included in our research demonstrated significant correlations between the biomarkers IL-6 and TNF-alpha and the modified Rankin Scale, highlighting the crucial role of inflammation in the disability prognosis of stroke patients." (PMID 39859987, 2025). "Studies have shown that the levels of acetic, propionic, and butyric acids are lower in stroke patients and older individuals, and butyric acid mitigates the production of TNF-α and IL-6 induced by LPS." (PMID 40004026, 2025). "A collaborative multi-functional nanoparticle combining NAC with dual action (TNF-alpha inhibition) has shown that in pre-clinical models of stroke and AD can reduce oxidative stress and neuro-inflammation at the same time." (PMID 40806624, 2025). "Preclinical studies show that inhibiting TNF-α can improve cognitive function and reduce neuroinflammation in animal models of AD and stroke, highlighting its potential as a therapeutic target for neurovascular diseases [1230, 1236]." (PMID 40407975, 2025). "Immediately after the stroke, there is a rapid activation of the peripheral immune system characterized by upregulation of proinflammatory cytokines such as IL‐1β, IL‐6, TNF‐α, and IFN‐c, as well as chemokines, C‐C motif chemokine ligand (CXCL)‐1 and CXCL‐2." (PMID 40804606, 2025).